ANGPTL3 (angiopoietin like 3)
Diseases named in the same sentence as ANGPTL3 in open-access papers (continued):
Sharing a sentence is not in itself a finding about the gene and the disease.
coronary artery disease (continued). "An observational study reports that human subjects harboring loss-of-function ANGPTL3 mutations show decreased serum ANGPTL3 protein levels, as well as decreased TG, LDL-cholesterol, and HDL-cholesterol, as well as lower incidence of coronary artery disease." (PMID 29538435, 2018). "Genome-wide association studies have confirmed the involvement of non-coding angiopoietin-like 3 (ANGPTL3) gene variants with coronary artery disease, levels of low-density lipoprotein cholesterol (LDL-C), triglycerides and ANGPTL3 mRNA transcript." (PMID 26800306, 2016). "ANGPTL3 LOF mutations reduce risk for developing Type 2 Diabetes (T2D) and coronary heart disease." (PMID 38344397, 2024). "The DisovEHR human genetics study reported an odds ratio of 0.60 (0.41–0.86) for coronary artery disease in carriers versus noncarriers of ANGPTL3 loss-of-function variants." (PMID 33716107, 2021). "However, concerns about the safety of inactivation of ANGPTL3 in patients with coronary artery disease (CAD) especially myocardial infarction (MI) have been raised." (PMID 30086775, 2018). "In a human-genetics sequencing study conducted with 58,335 participants, analysis showed that those who were heterozygous for ANGPTL3 loss-of-function variants had around 50% lower ANGPTL3 levels than noncarriers and a nearly 40% lower chance of coronary artery disease." (PMID 38675122, 2024). "Inhibition of ANGPTL3 activity leads to an important reduction in all major lipoprotein types, and loss-of-function (LOF) variants of ANGPTL3 were associated with a protective role against cardiovascular disorders, decreasing the risk of coronary heart disease by 34%." (PMID 35456556, 2022). "Higher serum levels of ANGPTL3 were detected in patients with OSA and coronary artery disease (CAD) compared to the patients having OSA alone." (PMID 36359273, 2022). "This study evaluated the relationship between serum ANGPTL3 level and peripheral arterial stiffness (PAS) in patients with coronary artery disease (CAD)." (PMID 34684048, 2021). "Genetic epidemiology shows that the functional absence of ANGPTL3 is strongly associated with reduced LDL levels, decreased triglyceride-enriched lipoproteins, and a lower risk of coronary artery disease." (PMID 40001219, 2025). "We conclude that therapies specifically aimed at decreasing plasma ANGPTL3, ANGPTL4, and APOC3 levels are expected to reduce the risk of coronary artery disease without raising safety concerns." (PMID 38895109, 2024). "Lipid metabolism related factors, such as angiopoietin‐like protein 3 (ANGPTL3), angiopoietin‐like 4 (ANGPTL4), fatty acid‐binding protein 4 (FABP4) are newly discovered factors that can affect coronary artery disease (CAD)." (PMID 38425231, 2024). "Also, the fact that the ANGPTL3/8 Ab reduced LDL cholesterol and APOB levels in patients strongly suggests that it could prove to be effective in preventing coronary heart disease." (PMID 37824203, 2023).
hyperlipidemia (37 papers, 2015 to 2025). "This reduction was closely associated with a decline in podocin expression, indicating the potential role of ANGPTL3 in hyperlipidemia-associated podocyte injury." (PMID 39061837, 2024). "This study establishes the link between ANGPTL3 and lipoprotein metabolism, indicating that the reduced ANGPTL3 expression reduces the risk of hyperlipidemia and ASCVD." (PMID 38344397, 2024). "Angiopoietin-like 3 (ANGPTL3) is another intriguing hyperlipidemia target, as evidenced by research showing that loss-of-function variations are linked to significantly lower LDL-cholesterol and triglyceride levels and a decreased risk of CHD." (PMID 37371099, 2023). "In this study, the data further confirm that glomerular ANGPTL3 expression is enhanced in a mouse model of renal injury associated with hyperlipidemia." (PMID 36123608, 2022). "Angptl3 ASO-mediated reduction in HDL-C was limited to the model with moderate lipidemia, where the majority of plasma cholesterol was associated with HDL." (PMID 34371033, 2021). "The striking hypolipidemic phenotype in ANGPTL3 deficiency shows the potential of ANGPTL3 inactivation as a treatment for correcting hyperlipidemia." (PMID 26754661, 2016). "Angiopoietin-like 3 (ANGPTL3) represents a compelling target for hyperlipidaemia, as studies indicate that loss-of-function variants are associated with markedly reduced LDL-cholesterol and triglyceride levels, along with a diminished risk of coronary heart disease (CHD)." (PMID 40463932, 2025). "ANGPTL3 could play a role in the mechanism of hyperlipidemia-associated podocyte injury via ACTN4." (PMID 36123608, 2022). "ANGPTL3 inhibitors demonstrate promise in mixed hyperlipidemia by exerting favourable effects across the full range of atherogenic lipoproteins." (PMID 41012446, 2025). "For mixed hyperlipidemia, progress in the field of human genetics has pinpointed angiopoietin-like 3 (ANGPTL3) as a potential key for mitigating cardiovascular hazards." (PMID 40001219, 2025). "Our findings bear discussion in the context of recent clinical trials testing pharmacologic ANGPTL3 inhibition for the treatment of refractory hyperlipidemia." (PMID 38219820, 2024). "Proteinuria is the main clinical manifestation of nephrotic syndrome and is closely related to the progressive deterioration of renal function and previous findings showed that ANGPTL3 was correlated with both hyperlipidemia and proteinuria." (PMID 37266537, 2023). "Recently, we also reported that Angptl3 transgenic mice exhibited hyperlipidemia and proteinuria, and TEM showed that the podocyte FPs were effaced." (PMID 36123608, 2022). "Consistently, in patients with hyperlipidemia, the expression of ANGPTL3, APOA1, TG, and LDL is increased, while PPARα is decreased." (PMID 35755170, 2022). "ACTN4 is a potential signaling molecule for ANGPTL3 in the mechanism of hyperlipidemia-related kidney injury." (PMID 36123608, 2022). "In patients suffering from hyperlipidemia and impaired renal function, inhibitors of ANGPTL3 were used to reduce serum lipids, thereby improving the renal function of the patient to improve the function of the kidney." (PMID 36123608, 2022). "Recently, study found that the serum and urine ANGPTL3 levels of patients with hyperlipidemia-induced renal injury remarkedly enhanced compared to those of healthy controls." (PMID 36123608, 2022). "Based on the reported data, we thinked that some molecules, such as ANGPTL3, played multiple roles not only in proteinuria but also in hyperlipidemia." (PMID 35399079, 2022).
hyperlipidemia (continued). "In this hyperlipidemia-related renal injury mouse model, with prolonged high-fat feeding time, the expression of ANGPTL3 gradually increased, and podocyte FPs fusion was increased accordingly." (PMID 36123608, 2022). "Our experiments showed that a large amount of ANGPTL3 was synthesized by hepatocytes in the context of nephropathy and participated in the occurrence of hyperlipidemia." (PMID 35399079, 2022). "In the previous study, we reported that serum ANGPTL3 was significantly enhanced in patients with hyperlipidemia-related kidney injury." (PMID 36123608, 2022). "One of the most promising one for the treatment of hyperlipidemias is angiopoietin-like 3 (ANGPTL3) which regulates the activity of lipoprotein (LPL) and endothelial lipases (EL) in peripheral tissues." (PMID 34146172, 2021). "ANGPTL3 inhibition therapy gives new hope for the treatment of hyperlipidemias and atherosclerotic CVDs." (PMID 34146172, 2021). "This study analyzed the relationship between ANGPTL3 and renal damage related indicators in hyperlipidemia population, hoping to provide the new ideas for revealing the occurrence of hyperlipidemia related proteinuria." (PMID 31103046, 2019). "It was important to confirm that there was the positive correlation between serum ANGPTL3 level and 24hUPro in patients with hyperlipidemia related proteinuria by Spearman correlation analysis." (PMID 31103046, 2019). "BMI, TC, TG and LDL in patients with hyperlipidemia related proteinuria were positively correlated with serum ANGPTL3." (PMID 31103046, 2019). "In order to understand the relationship between serum ANGPTL3 level and renal damage index in hyperlipidemia group, this study analyzed BUN, SCr and 24hUPro." (PMID 31103046, 2019). "In this study, we hoped to investigate the changes of Angiopoietin-like protein 3(ANGPTL3) levels in hyperlipidemia patients with different proteinuria levels." (PMID 31103046, 2019). "Our results were consistent with previous studies suggesting that ANGPTL3 was a sensitive expression indicator in patients with clinical hyperlipidemia." (PMID 31103046, 2019). "This study focused on the characteristics of serum ANGPTL3 expression in patients with hyperlipidemia and complicated with proteinuria and its relationship with renal damage related indicators." (PMID 31103046, 2019). "The expression level of serum ANGPTL3 in patients with hyperlipidemia related proteinuria was significantly higher than that in normal healthy subjects, and there was significantly positively correlated with the 24hUPro level of patients." (PMID 31103046, 2019). "We can also observe a significant hypolipidemic phenotype in the carriers of ANGPTL3 LOF mutations, suggesting that ANGPTL3 LOF mutations can be served as a target for hyperlipidemia." (PMID 29334984, 2018). "The region is an interesting target knowing that ANGPTL3 regulates plasma lipid levels and is a potential therapeutic target to treat combined hyperlipidemia." (PMID 29619113, 2018). "Hepatic miR-27b is increased in response to hyperlipidemia and, in turn, regulates several key genes in control of lipid metabolism (Angptl3, Gpam)." (PMID 26161255, 2015). "Currently, inhibitors of ANGPTL3 have been extensively studied in cardiovascular disease, and suppression of ANGPTL3 is protective in nephrotic syndrome; in the future, this inhibitor would be a candidate for hyperlipidemia-related kidney injury." (PMID 36123608, 2022). "Our results demonstrated that high ANGPTL3 expression could lead to nephropathic manifestations, such as proteinuria, with increasing age, which suggests that ANGPTL3 participates in the development of both hyperlipidemia and proteinuria in mice." (PMID 35399079, 2022).
hyperlipidemia (continued). "We wanted to explore how angiopoietin-like 3 (ANGPTL3) impact hyperlipidemia-induced renal injury." (PMID 36123608, 2022). "In summary, our study suggests that ANGPTL3 may participate in renal injury in hyperlipidemia and that ACTN4 is its target molecule in this mechanism." (PMID 36123608, 2022). "However, because ANGPTL3 inhibitors are being developed to treat preexisting hyperlipidemia in broad populations at risk for ASCVD, it is of interest to determine the effect of ANGPTL3 inhibition on not only HDL-C but also HDL function, particularly RCT." (PMID 34371033, 2021). "ANGPTL3 was highly expressed in patients with hyperlipidemia and may be a molecule that interferes with the occurrence of proteinuria in hyperlipidemia, which has been issued by our research group." (PMID 31103046, 2019). "Alisol B 23-acetate intervened the downstream regulators of FXR such as SREBP1c, PPARα, and genes involved in triglyceride metabolism (ApoC-II, ApoC-III, and angiopoietin like ANGPTL3), contributing to the improvement of hyperlipidemia as well as hepatic steatosis." (PMID 31275407, 2019). "Whether hyperlipidemia patients combined hypertension will aggravate the abnormal expression of ANGPTL3 is the question to be worth paying attention to study." (PMID 31103046, 2019). "With the increase of TC, TG and LDL levels, serum ANGPTL3 levels increased, suggesting that hyperlipidemia may due to the increasing expression of serum ANGPTL3." (PMID 31103046, 2019). "Whether ANGPTL3 participates in the occurrence of proteinuria in patients with hyperlipidemia was our key concern." (PMID 31103046, 2019). "The serum ANGPTL3 level increases with the increase of urinary protein, suggesting that ANGPTL3 might be involved in occurrence of lipemia proteinuria." (PMID 31103046, 2019). "ANGPTL3 is a potential therapeutic target for alternative treatment of combined hyperlipidemia." (PMID 26754661, 2016). "As a result, targeted inhibition of ANGPTL3 using a monoclonal antibody (evinacumab), an antisense oligonucleotide (ASO), and other pharmacologic strategies is an emerging therapeutic approach for treating refractory hyperlipidemia and potentially lowering cardiovascular disease risk." (PMID 38219820, 2024). "Interestingly, ANGPTL3 showed a relation with proteinuria in patients with hyperlipidemia." (PMID 37312105, 2023). "Our group discovered that ANGPTL3 was presented in cytoplasm of podocytes of glomeruli and tubular epithelial cells of rat kidney, ANGPTL3 level was found to be upregulated, and it was correlated with proteinuria and hyperlipidemia in ADR-induced nephrotic rats." (PMID 37266537, 2023). "Inhibition of LPL expression may the mechanism by which ANGPTL3 induces hyperlipidemia in PNS." (PMID 35399079, 2022). "Finally, we explored the role of LPL in the mechanism of ANGPTL3 in PNS hyperlipidemia." (PMID 35399079, 2022). "ANGPTL3 may be involved in the glomerular injury induced by hyperlipidemia." (PMID 36123608, 2022). "Inhibiting LPL expression may be the mechanism by which ANGPTL3 induces hyperlipidemia in PNS." (PMID 35399079, 2022). "ANGPTL3 might be involved in the formation of hyperlipidemia proteinuria." (PMID 31103046, 2019). "In ANGPTL3-knockout mice fed an HFD, there was a notable reduction in hyperlipidemia and proteinuria." (PMID 39061837, 2024). "In our study, we explored the dual roles of ANGPTL3, which is involved not only in the occurrence of PNS proteinuria but also in hyperlipidemia." (PMID 35399079, 2022).
hyperlipidemia (continued). "Angiopoietin-like 3 (ANGPTL3) is a secreted protein with multiple functions involving in promoting neovascularization and hyperlipidemia." (PMID 36229446, 2022). "As the key inhibitors of LPL, the ANGPTL family members ANGPTL3 and ANGPTL4 interfere with LPL activity in different ways, leading to increased levels of TG, TC, and LDL and the development of hyperlipidemia." (PMID 33853533, 2021). "ANGPTL3, ANGPTL4, and ANGPTL8 are important factors in the regulation of the metabolism of lipids and lipoproteins, providing new hope for the treatment of hyperlipidemia." (PMID 32440963, 2020). "Variants in ANGPTL3 (SLP = −12.68) and ANGPTL4 (SLP = −4.79) also appear to be protective against hyperlipidaemia, although the result for ANGPTL4 is not exome-wide significant." (PMID 38454133, 2024). "Furthermore, the degree of hyperlipidemia, as indicated by triglyceride, CHO and LDL-C levels, was correlated with the patients’ ANGPTL3 levels." (PMID 35399079, 2022). "ANGPTL3 can play a role through ACTN4 in a hyperlipidemia-related kidney injury model has not been reported." (PMID 36123608, 2022). "However, whether ANGPTL3 is involved in the development of hyperlipidemia proteinuria had not been confirmed." (PMID 31103046, 2019).
diabetes (33 papers, 2016 to 2025). "It should be noted that endothelial lipase is also a target of ANGPTL3, and it has been implicated in fetal growth in pregnancies complicated by diabetes and in intrauterine growth retardation." (PMID 36768809, 2023). "The ANGPTL3 variants are associated with lower levels of irisin and c-peptide and thereby act as protective variants for diabetes and metabolic disorders." (PMID 34067751, 2021). "In summary, our study of patients with diabetes revealed that ANGPTL3, 4, and 8 are associated with high TG levels and low HDL-C levels." (PMID 34293055, 2021). "The purpose of this study was thus to clarify the interactions among circulating ANGPTL3, 4, and 8 levels, their association with lipid and glucose metabolism markers, and the contributing factors to plasma TG levels in patients with diabetes." (PMID 34293055, 2021). "We investigated the correlation among circulating ANGPTL3, 4, and 8 levels and the association between ANGPTLs and markers of lipids, as well as glucose metabolism, in patients with diabetes." (PMID 34293055, 2021). "Heterozygous and homozygous carriers of ANGPTL3 loss-of-function mutations have reduced risk for type 2 diabetes mellitus." (PMID 30944669, 2019). "Roles of ANGPTL3, 4, and 8 in dyslipidaemia, obesity, and diabetes, diseases that are closely associated with OSA, are well-established." (PMID 30524367, 2018). "This study aimed to examine whether rs11207997 in ANGPTL3 is associated with a 10-year risk of diabetes mellitus (DM) and if the association is modified by the consumption of certain food groups or nutrients." (PMID 30683883, 2019). "Clinical observations in diabetes further show that high circulating ANGPTL8 associates with higher triglyceride levels and insulin resistance, and that concurrent high ANGPTL3 and ANGPTL8 identifies elevated TG and LDL." (PMID 41226996, 2025). "Silencing mouse APOC3 by a liver-targeted antisense oligonucleotide lowers both cholesterol and triglycerides carried by TRL/remnants and LDL and prevents aortic free cholesterol accumulation in diabetes, while ANGPTL3 silencing reduces triglycerides." (PMID 40709279, 2025). "Research indicates that the expression levels of serum ANGPTL3 positively correlate with the stage of diabetic retinopathy (DR) in individuals with type 2 diabetes mellitus (T2DM), implying its potential use as a biomarker for tracking the progression of DR." (PMID 40559376, 2025). "LPL was significantly down-regulated and the LPL regulators Angptl3 and Angplt4 were significantly up-regulated in diabetes." (PMID 39630889, 2024). "In a double-blind placebo-controlled dose-ranging phase 2 study, vupanorsen, an siRNA targeted to liver ANGPTL3, was evaluated in 105 patients with symptoms of triglyceridemia, diabetes and steatohepatitis." (PMID 37371118, 2023). "This multivariate analysis was controlled for blood urea nitrogen, creatinine, total cholesterol, triglyceride, alkaline phosphatase, Kt/V, sex, age, body mass index, diabetes mellitus, hypertension, hemodialysis duration, and ANGPTL3." (PMID 38276267, 2023). "However, no further investigations regarding the influence of the genetic variation of rs11207997 in ANGPTL3 on glucose metabolism and clinical endpoints including diabetes mellitus (DM) risk have been reported." (PMID 30683883, 2019). "In this study we show an opposite association pattern of serum ANGPTL3 and ANGPTL4 with body weight, diabetes status, and parameters of glucose control across a wide range of BMI as well as their different reactions to short- and long-term weight-modifying interventions." (PMID 29695708, 2018). "The decrease of ANGPTL3 level in female diabetes patients might be involved in the impaired HDL metabolism and function." (PMID 27620179, 2016). "In addition, there is evidence of change in circulating ANGPTL3 in patients with diabetes mellitus." (PMID 37312105, 2023).